CS (citrate synthase)
Diseases named in the same sentence as CS in open-access papers (continued):
Sharing a sentence is not in itself a finding about the gene and the disease.
infection (22 papers, 2010 to 2025). The state of being infected such as from the introduction of a foreign agent such as serum, vaccine, antigenic substance or organism. "However, after the CTSL cleavage sites were mutated to glycine in CS mutant, these PsVs gradually lost most of their infection ability in all four cell lines." (PMID 35668062, 2022). "In the present study, the isocitrate lyase and citrate synthase genes involved in the glyoxylate pathway were induced when T. rubrum was cocultured on keratinocytes, suggesting that this pathway is important for the process of infection caused by dermatophytes." (PMID 26257814, 2015). "We quantified the bacterial load using citrate synthase-based qPCR assay to ensure that both strains had similar levels of infection at all time points." (PMID 35409212, 2022). "A recent research demonstrated that citrate synthase contributes to infection and stress resistance of the stripe rust fungus." (PMID 33193272, 2020). "The aim of this study was to evaluate the diagnostic potential of recombinant cold shock H. contortus protein (rHc-CS) during early and late infections of H. contortus in goat." (PMID 32013987, 2020). "S. aureus. infection increased mitochondrial mass within the kidney characterized by elevated citrate synthase and mitochondrial GFP fluorescence." (PMID 24988481, 2014). "Additionally, the TCA cycle genes assessed presented the described decrease of expression starting at day post infection 3 and continued downregulated up to day post infection 8, including CS, Ogdh, and Suclg1 or day post infection 4, as observed in Sdhb." (PMID 37679643, 2023). "Similarly, WT infection impairs CS and complex I–III activities, which denote a commitment to oxidative phosphorylation." (PMID 34485182, 2021). "Forty-eight hours after infection, mRNA was isolated and CS gene expression was examined." (PMID 22485150, 2012). "Combine use of immunoblotting and indirect ELISA showed that rHc-CS is a specific, sensitive, and potential immunodiagnostic antigen which may consistently detect H. contortus antibodies in goats during early as well as late infection of H. contortus." (PMID 32013987, 2020). "The evaluation of CS activity, a mitochondrial content marker enzyme, revealed an impairment of 52.5% and 37.3% after WT and WTR infections, respectively." (PMID 34485182, 2021). "Moreover, the mRNA expression of citrate synthase (CS) and succinate dehydrogenase subunit A (SDHA), two key enzymes in the tricarboxylic acid cycle (TCA), was found to be distinctly higher post infection (both P < 0.001)." (PMID 34552973, 2021). "The sera of all H. contortus-infected goats had detectable antigenicity at 21, 35, 49, 63, 85, and 103 days of infection, no IgG antibody against rHc-CS was detected in sera collected at day pre-infection and 7 D.P.I." (PMID 32013987, 2020). "Although salinity or infection by OsHV-1 do not influence CS activity in oyster, the interaction of salinity and OsHV-1 on CS has never been investigated." (PMID 29463513, 2018).
bacterial infection (3 papers, 2021). "In oysters, it has been described that a bacterial infection triggering massive mortality events during larval development activates defenses and induces a decrease in certain parameters related to energy production, such as the activity of the mitochondrial enzyme citrate synthase (CS)." (PMID 34539443, 2021).
mitochondrial disease (3 papers, 2017 to 2021). "Antioxidant supplementation significantly increased Citrate Synthase activity [F(1.44) = 7.37, p < 0.01] but also interacted with the mitochondrial disease subgroup [F(1.44) = 8.30, p < 0.01]." (PMID 28208802, 2017). "Fatty acid supplementation significantly increased Citrate Synthase activity [F(1.44) = 9.58, p < 0.005] but also interacted with the mitochondrial disease subgroup [F(1.44) = 4.69, p < 0.05]." (PMID 28208802, 2017). "Citrate synthase activity was increased by antioxidant supplementation but only for the mitochondrial disease subgroup." (PMID 28208802, 2017). "Fatty acids, folate and antioxidant supplementation influenced Citrate Synthase activity with this influence being different for the mitochondrial disease subgroup." (PMID 28208802, 2017). "Folate supplementation significantly increased Citrate Synthase activity [F(1.44) = 7.00, p = 0.01] but also interacted with the mitochondrial disease subgroup [F(1.44) = 7.56, p < 0.01]." (PMID 28208802, 2017). "The results suggest that changes in CI and citrate synthase activities can be observed in buccal swabs in response to common interventions and that increased activity in these enzymes was more discernable in the mitochondrial disease subgroup." (PMID 34575097, 2021). "Results from this study suggested that several common mitochondrial supplements such as fatty acids and antioxidants appeared to influence Complex I and Citrate Synthase activity, respectively, with this influence being more marked for the mitochondrial disease subgroup." (PMID 28208802, 2017). "Folate has also been reported to increase ETC Complex I activity in children with ASD and mitochondrial disease and positively modulate the coupling of ETC Complex I and IV and ETC Complex I and Citrate Synthase." (PMID 34834493, 2021). "In a study of ASD children with or without mitochondrial disease, CI, CIV, and citrate synthase activity in response to fatty acid and folate supplementation was measured in buccal extracts." (PMID 34575097, 2021).
neurodegenerative disease (3 papers, 2015 to 2023). A disorder of the central nervous system characterized by gradual and progressive loss of neural tissue and neurologic function. "The same biochemical outcomes, except for mitochondrial mass (CS activity) and αGP-mediated respiration, correlated with FXTAS severity (i.e., stage) indicating that the morbidity of this neurodegenerative disease is also reflected as a peripheral deficit in bioenergetics." (PMID 33195422, 2020).
cardiovascular diseases (1 paper, 2020). "This view is supported by the finding that IgG NAb against citrate synthase (CS) in the pericardial fluid (PF) correlated with antibody titers against pathogens associated with cardiovascular diseases, whereas anti-CS IgM NAb were not." (PMID 33013904, 2020).
skeletal dysplasia (1 paper, 2017). Any Mendelian diseases that affects growth and development of the skeleton. "As new skeletal dysplasia loci are defined, the candidate genes can be compared with the CS genes to promote rapid identification of the mutated gene." (PMID 29262782, 2017). "In this context, we compared the CS genes with the genes associated with human genetic skeletal disorders, expecting that many of the genes would be associated with skeletal dysplasias." (PMID 29262782, 2017).
CS also shares sentences with these, for which no sentence is quoted: benign tumors (3 papers); Atrophy (2); breast adenocarcinoma (2); Hypertension (2); leukemia (2); measles (2); peritonitis (2); subarachnoid hemorrhage (2); adrenal gland diseases (1); age-related hearing loss (1); anisakiasis (1); atherosclerosis (1); atrial fibrillation (1); benign ovarian tumors (1); Bradycardia (1); brain tumor (1); Burkitt lymphoma (1); cartilage disorders (1); cholangiocarcinoma (1); chondrodysplasia (1); cognitive deficits (1); colorectal tumor (1); Cowden syndrome (1); deafness (1); dengue (1); dermatomyositis (1); edema (1); epilepsy (1); fibromyalgia (1); gastric cancer (1).
A further 30 diseases each share a sentence with CS in 1 paper.